HEATR5B (HEAT repeat containing 5B)
Description:
Component of clathrin-coated vesicles. Component of the aftiphilin/p200/gamma-synergin complex, which plays roles in AP1G1/AP-1-mediated protein trafficking including the trafficking of transferrin from early to recycling endosomes, and the membrane trafficking of furin and the lysosomal enzyme cathepsin D between the trans-Golgi network (TGN) and endosomes.
Synonyms: KIAA1414; p200; p200a; DKFZp686P15184
Tractability: PROTAC: ubiquitination databases record sites on it; its protein half-life has been measured.
Gene: Protein-coding gene on chromosome 2 (36,968,383 to 37,084,398, reverse strand). Ensembl gene ENSG00000008869.
Subcellular location: Cytoplasm, perinuclear region; Cytoplasmic vesicle, clathrin-coated vesicle
Subcellular location (Human Protein Atlas): Golgi apparatus; Vesicles; Cytosol; Nucleoplasm
Gene Ontology:
Molecular function: protein binding
Biological process: endocytosis; intracellular protein localization; retrograde transport, endosome to Golgi
Cellular component: Golgi apparatus; membrane; endocytic vesicle; clathrin-coated vesicle; cytosol; perinuclear region of cytoplasm
Genetic constraint (gnomAD): Loss-of-function variants: 101 observed, 154.97 expected, observed/expected ratio (o/e) 0.65, 90% interval 0.55 to 0.77. The upper end of that interval is the gene's LOEUF score, 0.77, which puts it in group 3 of 6, group 1 being the genes least tolerant of losing a copy. Missense variants: 1,814 observed, 2,059.5 expected, observed/expected ratio (o/e) 0.88, 90% interval 0.85 to 0.92. Synonymous variants: 789 observed, 744.05 expected, observed/expected ratio (o/e) 1.06, 90% interval 1 to 1.12.
Homologues: Orthologues: chimpanzee HEATR5B (99% identical), macaque HEATR5B (99% identical), dog HEATR5B (98% identical), pig HEATR5B (97% identical), rat Heatr5b (96% identical), mouse Heatr5b (96% identical), rabbit HEATR5B (95% identical), tropical clawed frog heatr5b (87% identical), guinea pig HEATR5B (87% identical), zebrafish heatr5b (79% identical), Drosophila melanogaster CG2747 (51% identical), Caenorhabditis elegans soap-1 (37% identical). Paralogues in human: HEATR5A (58% identical).
Diseases named in the same sentence as HEATR5B in open-access papers:
HEATR5B is named in the same sentence as 6 diseases in open-access papers, as found by Europe PMC text mining. Sharing a sentence is not in itself a finding about the gene and the disease. The quoted sentences say what the papers report.
pontocerebellar hypoplasia (1 paper, 2023). Pontocerebellar hypoplasias (PCH) are a rare heterogeneous group of diseases characterized by hypoplasia and atrophy and/or early neurodegeneration of the cerebellum and pons. "The importance of HEATR5B proteins is underscored by the recent finding that hypomorphic mutations in the human gene are associated with the neurodevelopmental syndrome pontocerebellar hypoplasia." (PMID 37872872, 2023).
tumor (2 papers, 2016 to 2023). "As a tumor suppressor gene, ZCRB1 phosphorylates JMJD5 to regulate aerobic glycolysis in GBM through the cyclic RNA HEATR5B." (PMID 36909185, 2023).
HEATR5B also shares sentences with these, for which no sentence is quoted: cancer (1 paper); glioblastoma (1); glioma (1); lipoma (1).